CXCR4 (C-X-C motif chemokine receptor 4)
Diseases named in the same sentence as CXCR4 in open-access papers (continued):
Sharing a sentence is not in itself a finding about the gene and the disease.
pancreatic cancer (continued). "It has also indicated that human pancreatic cancer cells with a high metastatic potential have been shown to upregulate the expression of CXCR4, but not CCR7, resulting in lung and liver metastasis in vivo, and a CXCR4 inhibitor suppressed the metastasis." (PMID 33406809, 2021). "Thus, CD133, EpCAM, CD44, and CXCR4 are commonly used to isolate and examine the involvement of the CSC population in pancreatic cancer progression and constitute prime targets for the treatment." (PMID 33946266, 2021). "The latest data suggest that inhibiting the interaction between CXCR4 expressing T cells and CXCL12 secreting cells in the microenvironment may modulate anti-CTLA-4 or anti-PD-1 immunotherapy in pancreatic cancer and HCC." (PMID 33790943, 2021). "It was reported that CQ targeted pancreatic cancer stem cells via inhibition of CXCR4 and hedgehog signaling, and its inhibitory effect was not related to inhibition of autophagy." (PMID 32232002, 2020). "The addition of IL-17A to pancreatic cancer cells did not increase the subpopulation of cells expressing the typical stem cell markers such as CXCR4, ABCG2, and CD44." (PMID 32210079, 2020). "Cancer immune suppression in pancreatic cancer appears to be mediated by CXCL 12, the chemokine that binds to cancer cells and excludes T cells by a mechanism that is dependent on the CXCL 12 receptor CXCR4." (PMID 32466266, 2020). "Forming a paracrine loop of the VEGF-mediated expression of CXCR4 by endothelial cells and the CXCL12-induced expression of VEGF by endothelial cells, this pathway is believed to assist in pancreatic cancer progression by inducing angiogenesis and lymphangiogenesis." (PMID 32069809, 2020). "In conclusion, our study showed that c-Myc could promote the development of pancreatic cancer, and c-Myc downregulation could synergistically enhance the antitumor activity of bufalin by downregulating the HIF-1α/SDF-1/CXCR4 pathway." (PMID 32362830, 2020). "In pancreatic cancer, gemcitabine treatment activated NF-κB and HIF-1α via ROS-mediated activation of ERK1/2 and Akt, upregulating chemokine receptor 4 (CXCR4) expression and contributing to gemcitabine resistance by CXCR4/chemokine 12 (CXCL12) signaling." (PMID 32587480, 2020). "In colorectal cancer, CD26+ CSCs generated liver metastases following implantation into the mouse cecal wall; in pancreatic cancer, CD133+CXCR4+ CSCs were responsible for metastasis and the overexpression of CXCR4 enhanced the metastatic potential of pancreatic cancer cells." (PMID 30934773, 2019). "Also in pancreatic cancer it has been shown that the interaction between tumor and surrounding stroma, mediated by the CXCL12/CXCR4 axis, influences the tumor growth and its aggressiveness." (PMID 31275385, 2019). "Through our ELISA assay we measured levels of different exosome populations, in particular those carrying the ubiquitous CD9, CD81 and some markers already found in tumour exosomes of pancreatic cancer such as CD44v6, Tspan8, EpCAM, CD24, CXCR4, Integrins α6 and β4, CD133." (PMID 31048929, 2019). "Finally, we further determine the expression of the pancreatic cancer markers CD44, CD326 and CxCR4 by immunofluorescence and by western blotting." (PMID 31388092, 2019). "In pancreatic cancer, inhibition of the CXCL12/CXCR4 axis arrested cell growth and abrogated gemcitabine resistance as well as reduced tumor growth in animal models by blocking CXCR4-dependent mast cell migration." (PMID 30813533, 2019). "Based on these results, the MORPHEUS clinical trials were started including treatment arms combining immune-checkpoint inhibitors with CXCR4 inhibition (NCT03193190, NCT03281369 and NCT03337698 for pancreatic cancer, gastric cancer and non-small cell lung cancer, respectively)." (PMID 30622535, 2018).
pancreatic cancer (continued). "The aim of our study was to examine the important role of the axis in pancreatic cancer (PaCa) cells’ relationship with stromal cells in gemcitabine-resistant (GEM-R) tumors and to confirm the effectiveness of CXCR4 antagonists for the treatment of GEM-R PaCa cells." (PMID 27175473, 2016). "This hypothesis is supported by a study indicating that CXCR4 could promote EGFR activation and subsequent downstream ERK activation in pancreatic cancer." (PMID 25679210, 2015). "Cancer therapy using an anti-VEGF Ab upregulated CXCR4 in rectal cancer cells, and upregulation of CXCR4 and increased invasiveness mediated by reactive oxygen species, NF-κB, and HIF-1α was observed in pancreatic cancer cells treated by the chemotherapeutic agent gemcitabine." (PMID 26083776, 2015). "In addition, we found that GLI1 up-regulated CXCR4 expression in MCF-7 cells, as previously reported in medulloblastoma cells and pancreatic cancer cells." (PMID 26413813, 2015). "Virtually no pancreatic cancer cell possessed dual cell surface expression of SDF-1α receptors i.e. CXCR4 and CXCR7." (PMID 25821841, 2015). "Thus far, two CSC populations in pancreatic cancer have been shown to be metastatic, CD133+CXCR4+ and Met+CD44+." (PMID 25829252, 2015). "Similar negative correlations between CXCR4 expression and promoter methylation have been shown in pancreatic cancer and melanoma cells." (PMID 25114911, 2014). "In conclusion, our data suggest that the chemotactic interaction between CXCR4 and its ligand CXCL12 may be a critical event in the progression of pancreatic cancer." (PMID 23181100, 2012). "To date, the clinical significance of the CXCL12/CXCR4 axis in pancreatic cancer has not yet been clearly elucidated." (PMID 23181100, 2012). "The interaction between CXCR4 and CXCL12 may play crucial roles in the metastasis and progression of pancreatic cancer by its effects on the formation of new blood vessels and lymphatic vessels." (PMID 23181100, 2012). "The chemotactic interaction between CXCR4 and its ligand CXCL12 may be a critical event during the progression of pancreatic cancer." (PMID 23181100, 2012). "CXCR4 and CXCR7 expression was assessed in 7 pancreatic cancer cell lines by immunoblotting." (PMID 22472349, 2012). "In pancreatic cancer, CD133+/CXCR4+ cells are shown to be responsible for metastasis." (PMID 21347385, 2011). "In pancreatic cancer, CXCR4 methylation occurred in 46% of the tumors but did not display any significant associations with common clinicopathological factors, such as age, gender, stage or lymph node metastasis." (PMID 22220212, 2011). "Immunohistochemistry staining results showed that CXCR4 expression was detected not in the normal pancreatic cells but in the cytoplasm of most pancreatic cancer cells." (PMID 19002187, 2008). "Both studies concluded that TN14003 was a very effective inhibitor of the CXCR4/CXCL12 chemokine axis, and may be a possible future therapy for breast and pancreatic cancer." (PMID 18001467, 2007). "Pancreatic cancer is associated with many CSCs markers that are negative prognostic factors and associated with tumor recurrence and clinical progressions, such as CD133, CD24, CD44, CXCR4, and ESA." (PMID 35892853, 2022). "Moreover, it is possible that PD-L1 activities are connected to chemokine-related pathways also in other aspects, as evidenced by the association of PD-L1 with the chemokine CXCL9 in basal patients and by the cooperativity between CXCR4 (CXCL12 receptor) and PD-L1 inhibitors in pancreatic cancer." (PMID 35205789, 2022). "Pancreatic cancer, TME, contains various possible therapy targets, such as HA, focal adhesion kinase (FAK), connective tissue growth factor (CTGF), CD40, and chemokine (C-X-C motif) receptor 4 (CXCR-4), which could be utilized in future clinical applications." (PMID 33800172, 2021).
pancreatic cancer (continued). "Trafficking into pancreatic tumor microenvironment, endogenous CD8+ T cells reactivate recognition and destruction of neoplastic cells by the combination of programmed cell death protein 1 (PD-1) and C-X-C chemokine receptor type 4 (CXCR4) blockade as the basis for combination immunotherapy in PC." (PMID 34124046, 2021). "CXCR4 blocking strategies using antibodies or small inhibitors have proven to be effective to reduce metastatic burdens and a phase IIb clinical trial for a CXCR4 antagonist in combination with anti-PD1 therapy in advanced pancreatic cancer is ongoing (NCT02907099)." (PMID 31544819, 2019). "Interestingly, pancreatic stellate cells isolated from pancreatic cancer tissues do not express CXCR4." (PMID 31275385, 2019). "Moreover, we have demonstrated that SDF-1/CXCR4 signaling induces pancreatic cancer cell invasion and EMT through non-canonical activation of the Hedgehog pathway." (PMID 25557170, 2015). "Furthermore, we show that Nodal promotes pancreatic cancer cell migration and invasion, induces epithelial-mesenchymal transition (EMT) and enhances the expression of matrix metalloproteinase-2 (MMP2) and CXC chemokine receptor 4 (CXCR4)." (PMID 25557170, 2015). "Since current data suggests that AMD3100 may not be safe or effective as an anti-CXCR4 antagonist for therapeutic applications in pancreatic cancer, specific antagonists remain to be identified for this purpose." (PMID 22319600, 2012). "However, correlations between the CXCL12/CXCR4 axis and clinical features of pancreatic cancer have not been extensively studied." (PMID 23181100, 2012). "Having observed a role of CXCR4 activation in gemcitabine resistance and potentiation of survival pathways, we investigated if the small-molecule CXCR4 antagonist, AMD3100, could diminish CXCL12-induced chemoresistance in pancreatic cancer cells." (PMID 21045835, 2010). "Additionally, gemcitabine induces CXCR4 expression in pancreatic cancer cells indirectly by stimulating ROS, which in turn activates ERK1/2 and Akt and resultantly upregulates the nuclear factors NF-κB and HIF-1α that bind to and activate expression of the CXCR4 promoter." (PMID 37173915, 2023). "Furthermore, removal of CD133+CXCR4+ subset from CD133+ cancer stem cells could disrupt the metastasis of pancreatic cancer, but did not affect tumorigenesis in primary organ." (PMID 21542915, 2011). "In this study, the cytokine‒cytokine receptor interaction pathway was the most enriched pathway between pancreatic cancer cells treated with and without glutamine, includingCCL5,CCR4,LTA,CXCR4,IL-6R, andIL-7R." (PMID 36942991, 2023). "In CXCL12-treated pancreatic cancer cells, CXCR4 antagonist AMD3100 does not inhibit migration and invasion, indicating CXCR7 promotes pancreatic cancer cell migration and invasion." (PMID 35159011, 2022). "Taken altogether these data strongly suggest that in MiaPaCa-2 pancreatic cancer cells and in the presence of SELN6.0, Akt is likely a downstream target of the SDF-1α-CXCR4 axis rather than under Kras activity." (PMID 25821841, 2015).
melanoma (227 papers, 2007 to 2025). A malignant, usually aggressive tumor composed of atypical, neoplastic melanocytes. "The inhibition of CXCR4 has also been linked to suppressed melanoma growth and enhanced CD8+ T cell infiltration in in vivo models." (PMID 40649909, 2025). "It was discovered early on that CXCR4 expression in melanoma cells was correlated with poor prognosis and the risk of recurrence was 2.5-fold higher and death 3 times higher than those with low CXCR4 expression." (PMID 39982274, 2025). "The G-protein-coupled chemokine receptor CXCR4 expression in monocytes has been linked to pro-tumor effects, especially when co-cultured with tumor cells like ovarian cancer and melanoma." (PMID 38675738, 2024). "In summary, this study highlights the association of CXCR4 with RUNX2 expression in melanoma cells and its implications in melanoma invasiveness, osteotropism, and autophagy." (PMID 38474372, 2024). "CXCR4 is related to metastasis and lymph node spread and is associated with poor survival rates in melanoma and colorectal cancer." (PMID 36149322, 2022). "Compared to controls, Ccr10 and Cxcl12/Cxcr4 levels were decreased in B16 melanoma tumors from Cbx3/HP1γ-deficient mice." (PMID 34721405, 2021). "Mavorixafor (also called AMD11070) is a small molecule that is a selective and orally bioavailable antagonist of CXCR4 in Phase 1b/2a development in association with immune checkpoint inhibitors in melanoma (NCT02823405) and renal cancer (NCT02923531)." (PMID 32260318, 2020). "In this context, CXCR7 is apparently necessary to hold melanoma cells susceptible to SDF-1/CXCR4 signaling by working as SDF-1 neutralizer, thus keeping its gradient functionally active nearby the cell surface." (PMID 31324252, 2019). "In stage I-III melanoma patients, high expression of CXCR4 in circulating CD4+CD45RA+ was associated with prolonged disease free survival." (PMID 30420855, 2018). "Increased CXCR4-expressing macrophages were detected in the bone marrow of melanoma patients, which was associated with pro-angiogenic and immune-suppressive phenotypes." (PMID 29867925, 2018). "The expression of CXCR4 by melanoma cells in primary lesions is significantly associated with the presence of ulceration, increased tumor thickness and higher mortality rate." (PMID 24559071, 2014). "Meta analysis of 13 studies investigating overall CXCR4 expression in melanoma tissue (calculated by IHC staining or qPCR) in primary and metastatic tissue demonstrated that over expression of CXCR4 is associated with ulceration, increased thickness and lymph node spread." (PMID 39825956, 2025). "Additionally, the chemokine receptor CXCR4 is stated to be associated with cancer growth, invasion and metastasis and identified as an independent predictor of poor prognosis in primary melanoma." (PMID 35758810, 2022). "Moreover, increased hepatocyte CXCL12 expression is associated with increased CXCR4 (+) cells in melanoma and CRC liver metastasis presumably by promoting cancer cell invasion." (PMID 34298991, 2021). "We have shown that melanoma cells recruit Au-NPs-loaded ECFCs prepared from cord blood (CB) by the CXCR4 (expressed by ECFCs)-SDF-1 (produced by melanoma cells and associated MSCs) axis in 18 h, and that an anti-SDF-1 neutralizing antibody precludes ECFCs recruitment both in vitro and in vivo." (PMID 32630815, 2020). "Expression of the CXCL12/CXCR4 axis is increased in numerous cancer types, and it may serve as a diagnostic or prognostic biomarker in cancer patients, including those with melanoma." (PMID 27590504, 2016). "Gene expression studies at the mRNA level have shown that human melanoma cell lines express CXCR4 and also receptors CCR10 and CCR7 which could be implicated in the frequent metastasis of melanoma to skin and lymph nodes, respectively." (PMID 24559071, 2014). "CXCR4 is also associated with metastatic spread of melanoma." (PMID 24069584, 2013). "CXCR4 expression in primary melanoma is associated with disease progression." (PMID 24212610, 2010).
melanoma (continued). "Likewise, our previous study also showed that omega-3 metabolites protected against CXCR4-associated melanoma metastasis, indicating that omega-3-mediated inhibition of tumor metastasis may be associated with the reprogramming of TME." (PMID 36217054, 2023). "In addition, RhoE accelerates cell migration, invasion, and metastasis via increased CXC chemokine receptor 4 (CXCR4) expression in gastric cancer cells, and expression of RhoE in melanoma cells is associated with invasive behavior in a three-dimensional dermal-like environment." (PMID 33406809, 2021). "In addition to tumor cells, CXCR4 is expressed by several other cell types, including macrophages and endothelial cells, and the CXCL12—CXCR4 pathway is associated with tumor progression, metastasis, and angiogenesis, also providing an attractive target for melanoma therapy." (PMID 26918341, 2016). "CXCR4 has been shown to assist melanoma metastatis to bones, and exosomes from those cells were able to cause the upregulation of CXCR7 a member of the CXCL12/CXCR4/CXCR7 signalling axis to promote them to a more osteotropic phenotype." (PMID 39982274, 2025). "The C-X-C motif chemokine ligand 12 (CXCL12) and its receptor CXCR4 play a crucial role in the metastasis of melanoma." (PMID 41346595, 2025). "CXCR4, a chemokine receptor, is often overexpressed in various types of cancer, including kidney, lung, brain, prostate, breast, pancreas, ovarian, and melanomas." (PMID 40142155, 2025). "CXCL12, primarily secreted by stromal cells within the tumor microenvironment, binds to CXCR4 on the surface of melanoma cells, activating downstream signaling pathways that enhance tumor cell migration, invasion, and metastasis." (PMID 41346595, 2025). "In a meta-analysis of melanoma cancer patients, CXCR4 overexpression in melanoma cells was correlated with ulceration, tumour thickness, and lymph node metastasis, and is a strong prognostic biomarker for metastatic melanoma." (PMID 39982274, 2025). "In this regard, it is worth noting that previous work with a B16 mouse melanoma cell line expressing CXCR4, CCR5, and WT CD4 demonstrated that it was resistant to HIV-1 Env-mediated fusion because of the reduced CD4 lateral mobility in these cells." (PMID 40284914, 2025). "The use of a CXCR4 antagonist in a murine melanoma model showed antitumor effects that were additive when used in combination with an anti-PDL1 antibody." (PMID 39982274, 2025). "In melanoma, FTO knockdown increases m6A methylation of key oncogenes like PD‐1, CXCR4 and SOX10, promoting YTHDF2‐mediated mRNA degradation and making melanoma cells more susceptible to interferon‐γ and anti‐PD‐1 therapy." (PMID 39135292, 2024). "Significantly higher CXCR4 protein levels were uniformly distributed in HepPar1[+] cells (hepatocytes) in the ANH area compared with DNH or HMB45[+] (melanoma cells) tumour areas." (PMID 39496484, 2024). "In the present study, we used melanoma cells and a RUNX2 knockout (RUNX2-KO) in vitro model to assess the influence of RUNX2 on CXCR4 protein levels along with its effects on markers associated with cell invasion and autophagy." (PMID 38474372, 2024). "Our data suggest that RUNX2 promotes melanoma progression by upregulating CXCR4, and we identify the latter as a key player in melanoma-related osteotropism." (PMID 38474372, 2024). "These two approaches would provide proof-of-principle data strengthening the value of RUNX2 and CXCR4 as potential therapeutic targets against melanoma." (PMID 38474372, 2024). "After demonstrating the effect of RUNX2 on the expression levels of CXCR4, we sought to assess CXCR4’s impact on the formation of melanoma metastasis in the bone." (PMID 38474372, 2024). "In fact, our data indicate that RUNX2 induces the expression of CXCR4, which in turn promotes autophagy, cell invasiveness, and osteotropism, by inhibiting the mTOR signalling pathway in melanoma cells." (PMID 38474372, 2024).